ALB (albumin)
Diseases named in the same sentence as ALB in open-access papers (continued):
Sharing a sentence is not in itself a finding about the gene and the disease.
hypertrophy (16 papers, 2012 to 2025). Hypertrophy is the increase in the volume of an organ or tissue due to the enlargement of its component cells. "Clinical manifestations of DN are urine albumin excretion, glomerular hypertrophy, and glomerular fibrosis." (PMID 34066452, 2021). "Clinical manifestations of DN are glomerular hypertrophy, urine albumin excretion, glomerular fibrosis, and increased extracellular matrix (type I collagen and fibronectin) production." (PMID 34066452, 2021). "Osmolality, albumin, creatinine level in urine got worse in cardiac hypertrophy induced by ISO compared with control group." (PMID 34684485, 2021). "Patients with diastolic dysfunction and hypertrophy had lower levels of eGFR and albumin, while markers of fluid balance such as OH, OH/ECW, ECW/TBW, and NT-proBNP were significantly higher than in any of the other groups." (PMID 32730268, 2020). "Diabetic mice treated with curcumin, L2H21, or L50H46 also exhibited decreased level of cardiac hypertrophy proxy and urinary albumin excretion when compared to untreated diabetic mice." (PMID 31920992, 2019). "Features of early diabetic renal injuries are glomerular hyperfiltration, glomerular and renal hypertrophy, increased urinary albumin excretion, increased basement membrane thickness and mesangial expansion." (PMID 23658831, 2013). "Furthermore, a significant increase in kidney weight to body weight ratio, which reflects renal hypertrophy, proteinuria (mg/24 h), and elevated urine albumin to creatinine ratio (UACR; μg/mg), was noted in the untreated diabetic mice as compared to control mice." (PMID 36986825, 2023). "DN rats showed renal dysfunction, as evidenced by decreased serum albumin and creatinine clearance, along with increases in serum creatinine, blood urea nitrogen, TGF-β1, and kidney hypertrophy, and these were reversed by OP-D." (PMID 32520209, 2020). "Albumin was the lowest in patients with coexistence of AoAC and cardiomegaly (3.9 ± 0.6 mg/dL), while it was the highest in patients without AoAC or cardiomegaly (4.2 ± 0.5 mg/dL)." (PMID 25695046, 2015).
kidney injury (16 papers, 2012 to 2025). Trauma to the kidney. "Patients with kidney injury requiring PMV and RRT have lower baseline conditions, such as a high APACHE II score and low serum albumin, and kidney injury is associated with the deterioration of respiratory failure." (PMID 35566577, 2022). "We found that VSIG4 expression was upregulated and that it correlated with the urinary albumin level in the doxorubicin-induced kidney injury animal model." (PMID 36836636, 2023). "After induction of kidney injury, serum urea and creatinine, urinary albumin, kidney MDA and TGF-β1 levels increased in rats with both previous exercise and no previous exercise, while GFR, and kidney TAC and SIRT1 levels significantly decreased." (PMID 35236328, 2022). "In current times, biomarkers of kidney damage, such as changes in serum creatinine and eGFR and/or urinary albumin/protein excretion, apply to a later stage of kidney injury after substantial kidney injury has occurred." (PMID 32664269, 2020). "Those with early nephrotoxicity on the third day tended to receive a higher total dose of polymyxin B and concomitant tigecycline treatment, and had reduced baseline albumin levels (30.5 ± 5.4 g/L vs. 33.9 ± 5.5 g/L, p = 0.01) and pre-existing kidney injury." (PMID 33613276, 2020). "Likewise, the reduced expression of NHE3, which is partly responsible for the impaired reabsorption of albumin and calcium, is thought to be responsible for the increased urine albumin and calcium in the gentamicin-induced kidney injury group." (PMID 37237729, 2023). "Furthermore, the level of urinary VSIG4 was highly correlated with the level of urinary albumin in the doxorubicin-induced kidney injury mouse model." (PMID 36836636, 2023). "Thus, the data collectively suggested that exosome secretion was increased carrying albumin in tubule during proteinuric kidney injury." (PMID 32641688, 2020). "Finally, we identified that manipulating the approach of albumin handling in TECs may represent a novel approach of ameliorating proteinuric kidney injury." (PMID 32641688, 2020). "We therefore investigated the relationship between RHR and urinary albumin/creatinine ratio (UACR, an indicator of early kidney injury) in general population at different levels of blood pressure and blood glucose." (PMID 31534974, 2019). "S. nigra extract exhibits a protective effect in kidney injuries due to its high protein levels and seven essential amino acids, which probably directly inhibits the •O2−, H2O2, and HO• production and regulates albumin oxidation." (PMID 39861148, 2025). "Patients with kidney injury who underwent kidney biopsy were younger, had higher levels of serum creatinine and daily excretion of urinary protein and had a lower initial eGFR and serum albumin level than patients with kidney injury who did not undergo kidney biopsy." (PMID 34109201, 2021).
lung adenocarcinoma (16 papers, 2022 to 2026). A carcinoma that arises from the lung and is characterized by the presence of malignant glandular epithelial cells. "Therefore, our findings suggest that high D-dimer and low serum albumin are associated with an increased risk of PE recurrence in patients with lung adenocarcinoma." (PMID 41200633, 2025). "The fusion of human serum albumin with human lactoferrin (hLF-HSA) exerts strong anti-migratory effects in human lung adenocarcinoma cells through matrix metalloproteinase 1 (MMP1) downregulation." (PMID 41873731, 2026). "Higher anti-tumor activity was seen in A549 and H460 lung adenocarcinoma cell lines when bovine serum albumin and chitosan were used as the hybrid nanocarriers compared to when albumin alone was used." (PMID 39494247, 2024). "Two lung adenocarcinoma patients with KEAP1 received standard therapy of albumin paclitaxel + carboplatin + Coreda for 3 months after tumour proportion score (TPS) of PD-L1 Immunohistochemical test showed 95% and 90% respectively (Figure 7A1,A2)." (PMID 38962454, 2024). "Similarly, in advanced lung adenocarcinoma, patients with low albumin/D-dimer ratios (≤16.6) exhibited significantly lower disease control and overall response rates, as well as worse PFS." (PMID 40283046, 2025). "The chemotherapy regimens primarily consisted of single‐drug or platinum‐based chemotherapy chosen by physicians, including but not limited to platinum drugs, paclitaxel (paclitaxel liposome, albumin‐paclitaxel, docetaxel), gemcitabine, and pemetrexed (for lung adenocarcinoma only)." (PMID 38400661, 2024). "Therefore, actinonin encapsulated albumin nanoparticles-based therapy holds great potential as an alternative strategy to improve its anti-cancerous activity against lung adenocarcinoma." (PMID 35892161, 2022). "In conclusion, in this study, we discovered that gender, ALB, CEA, and Cyfra21‐1 are valuable prognostic variables in stage IA lung adenocarcinoma, which not only can help predict recurrence, but can also provide guidance for surgical practice." (PMID 37793977, 2023). "The copy numbers of both the target (CYP2C8, CYP3A4) and the reference genes (ALB, B2M, BCKDHA, F5, CD36, MPO, TBP, RPPH1) established in primary lung adenocarcinoma by the qPCR-based method were congruent with those determined by next-generation sequencing (for 10 genes, slope = 0.9498, r2 = 0.72)." (PMID 37686184, 2023). "We presented a 67-year-old nonsmoking female lung adenocarcinoma patient with novel epidermal growth factor receptor (EGFR) A289G/F287_G288insHA cis mutations who responded positively to sintilimab combined with regorafenib and albumin paclitaxel, and sequential treatment of icotinib." (PMID 35251994, 2022).
Microscopic hematuria (16 papers, 2014 to 2025). Microscopic hematuria detected by dipstick or microscopic examination of the urine. "His clinical picture fits with prior reports of rosuvastatin-associated AKI, with intermittent microhematuria and evidence for tubular toxicity with a relatively higher urine total protein/Cr compared with a more modest elevation of urine albumin/Cr ratios." (PMID 41356965, 2025). "Eleven (16.2%) patients had leukocyturia that met the diagnostic criteria, nineteen patients (27.9%) had microscopic hematuria, and thirty-five patients (51.5%) had positive albumin." (PMID 36553164, 2022). "The median proteinuria was 1.62 g/d (IQR, 0.90–2.22 g/d), median microhematuria was 3 RBCs/HPF (IQR, 1–8 RBCs/HPF), and the mean serum albumin was 3.22 g/dl (SD, 0.73 g/dl)." (PMID 34926493, 2021). "After multiple regression analyses, significant correlations were found among age, DBP, serum creatinine, estimated GFR, hemoglobin, serum albumin, UPCR, and presence of microscopic hematuria and anti-dsDNA antibody with renal pathological activity index." (PMID 25874130, 2015). "In comparison with other classes, patients with class IVG had a significant increase in serum creatinine, blood pressure, proteinuria, and frequency of microscopic hematuria and a significant decrease in estimated GFR, serum albumin, and hemoglobin." (PMID 25874130, 2015). "Clinical data at initial presentations including 24 hours urinary proteins, serum albumin, total serum cholesterol, arterial blood pressure and presence of microscopic hematuria were not significantly different between groups." (PMID 28975099, 2017). "SBP, DBP, BUN, serum creatinine, UPCR, and presence of serositis, microscopic hematuria, and anti-dsDNA were positively correlated with renal pathological activity index, whereas age, estimated GFR, hemoglobin, and serum albumin were negatively correlated with renal pathological activity index." (PMID 25874130, 2015). "Besides, the proband’s father (II:3) was affected with proteinuria [urinary albumin/creatinine ratio (ACR) 74.03 mg/mmol], microscopic hematuria with elevated serum creatinine level (138 μmol/L) (EPI-eGFR 46.5 ml/min/1.73m2) and increased uric acid level (611 μmol/L) at the age of 63." (PMID 36371311, 2022). "Besides, according to our subgroup analysis, a higher frequency of relapses was more common in patients with lower eGFR < 97.8 mL/min/1.73m2, serum albumin < 2.5 g/dL group, serum cholesterol ≧ 405 mg/dL, the presence of nephrotic-range proteinuria, and the absence of microscopic hematuria." (PMID 33435901, 2021).
osteosarcoma (16 papers, 1984 to 2025). A usually aggressive malignant bone-forming mesenchymal neoplasm, predominantly affecting adolescents and young adults. "These albumin NPs produced in vivo a temporary regression of an osteosarcoma model and increased survival." (PMID 34066953, 2021). "NPs based on bovine serum albumin, hydroxyapatite, and paclitaxel were prepared for in situ treatment of osteosarcoma by Liu and collaborators." (PMID 34066953, 2021). "Network pharmacology showed that 251 luteolin against osteosarcoma targets and 8 hub targets including AKT1, ALB, CASP3, IL6, JUN, STAT3, TNF, and VEGFA." (PMID 40066267, 2025). "In our study, serum albumin and TC levels were not independent prognostic factors for the survival of osteosarcoma patients, but they formulate a new scoring system of NPS which showed good prognostic performance when combined with NLR and LMR." (PMID 32000789, 2020).
pancreatic adenocarcinoma (16 papers, 2010 to 2025). "In our study, the cut-off value of albumin for patients with pancreatic adenocarcinoma was determined as 38.55." (PMID 40282930, 2025). "For patients with pancreatic adenocarcinoma, the cut-off point for the albumin value was 38.55, the cut-off point for the HALP value was 34.4, and the cut-off point for the LCR value was 0.61." (PMID 40282930, 2025). "In patients with pancreatic adenocarcinoma, we were able to show that inflammatory parameters as well as albumin can determine the prognosis earlier and more specifically than conventional methods." (PMID 38539528, 2024). "A phase II randomized clinical trial of GEM in combination with HCQ and albumin-bound-paclitaxel in metastasis or advanced pancreatic adenocarcinoma patients have also demonstrated an increased pathologic response rate with the combination." (PMID 37393350, 2023). "We investigated the prognostic usefulness of prechemoradiotherapy (CRT) albumin-to-alkaline phosphatase ratio (AAPR) in unresectable locally advanced pancreatic adenocarcinoma (LAPAC) patients managed with definitive concurrent CRT (CCRT)." (PMID 33927759, 2021). "More recently, the treatment options for metastatic pancreatic adenocarcinomas have increased with the approval of nab-paclitaxel (albumin-bound paclitaxel) as first line therapy in combination with gemcitabine." (PMID 27765912, 2016). "As recommended by the NCCN guidelines, treatment can be continued with a regimen of gemcitabine +albumin-bound paclitaxel for patients with patent biliary tracts and good nutritional status (NCCN Guidelines, Pancreatic Adenocarcinoma, Version 1, 2022)." (PMID 35847852, 2022). "Therefore, the aim of this study was to examine the correlation of albumin level, HALP scores and LCR values with survival and recurrence in patients with pancreatic adenocarcinoma." (PMID 40282930, 2025). "CA 19–9, carcinoembryonic antigen (CEA), C-reactive protein, albumin, insulin growth factor-1 (IGF-1) and IGF binding protein-3 were measured using routine clinical analyzers in a cohort of 47 pancreatic adenocarcinoma, 20 chronic pancreatitis and 15 healthy controls." (PMID 26808421, 2016).
squamous cell carcinoma (16 papers, 2010 to 2025). A carcinoma arising from squamous epithelial cells. "Low serum albumin has already been demonstrated to be associated with poor outcome in patients with squamous cell carcinoma, reflecting reduced nutritional and inflammatory status in those patients." (PMID 35482049, 2022). "A high level of albumin (≥40 g/l) was associated with a lower risk of squamous cell carcinoma." (PMID 37876941, 2023). "Higher genetically predicted Albumin levels were associated with a reduced risk of adenocarcinoma, while elevated MUFA levels were linked to an increased risk of squamous cell carcinoma." (PMID 40719999, 2025). "Clinical parameters with predictive factors for being a responder are female gender, a squamous cell carcinoma subtype, and normal pre-treatment serum albumin." (PMID 36766868, 2023). "Female gender, age ≥ 60 years, current smoking/ex-smoking status, ECOG score 0–1, pre-treatment serum albumin ≥ 3.5 mg/dL, and squamous cell carcinoma histology were included in the final model." (PMID 36766868, 2023). "Differences in age, intrapulmonary metastasis of 312 patients of squamous cell carcinoma and differences in age, sex, stages, pleural metastasis of 612 patients of adenocarcinoma between the two groups of serum albumin(P < 0.05)." (PMID 28302220, 2017). "Although significant associations between serum PD‐L1 levels and clinicopathological variables were observed, serum PD‐L1 level was significantly associated with high neutrophil counts, high CRP levels, low albumin levels, and high squamous cell carcinoma antigen levels." (PMID 31865635, 2020). "In different histological classification between the two groups of serum albumin, the median survival period of squamous cell carcinoma was 36 months and 19 monthes, adenocarcinoma was 35 months and 15 monthes, the abnormal group were all significantly lower than those in the normal group." (PMID 28302220, 2017). "Patients with stage IV or recurrent squamous cell carcinoma could be stratified by either serum albumin concentration or by age into 2 groups with a median survival of 1 or 2 years." (PMID 21176210, 2010). "Gamma-glutamyltransferase also showed a potential positive causal relationship with squamous cell carcinoma (β: 0.241, P: 0.009, FDR: 0.072), while non-albumin exhibited a potential negative causal relationship with squamous cell carcinoma (β: -0.272, P: 0.020, FDR: 0.180)." (PMID 39687887, 2024). "Serum albumin, HSP (Heat shock protein) 27, gamma actin, SCC (Squamous cell carcinoma) 1, and Annexin A4." (PMID 40256126, 2025). "The identified proteins were serum albumin, HSP (Heat shock protein) 27, gamma actin, SCC (Squamous cell carcinoma) 1, and Annexin A4." (PMID 34181340, 2021). "Serum albumin, Heat shock protein 27 (HSP 27), gamma actin, squamous cell carcinoma (SCC) 1, and Annexin A4 (ANXA4) were identified proteins and have a positive association with OSCC development." (PMID 34181340, 2021).
transient ischemic attack (16 papers, 2014 to 2025). A brief attack (from a few minutes to an hour) of cerebral dysfunction of vascular origin, with no persistent neurological deficit. "A meta-analysis including 13,618 patients with acute IS or transient ischemic attack concluded that low serum albumin levels could predict adverse functional outcomes and mortality in patients with these diseases." (PMID 37900597, 2023). "A recent national prospective study from China including >13,000 patients concluded that low albumin levels were related to poor functional outcome and higher mortality after acute ischemic stroke (AIS) and transient ischemic attack (TIA)." (PMID 38794724, 2024).
acute-on-chronic liver failure (15 papers, 2009 to 2025). Acute-on-chronic liver failure (ACLF) is an extreme condition during the natural history of chronic HBV infection, with a relatively high short-term mortality. "ADVanced Organ Support (ADVOS) is a novel type of extracorporeal albumin dialysis and holds promise to sustain liver function and recovery of patients with acute-on-chronic liver failure (ACLF)." (PMID 33793644, 2021). "Similar data on the effects of albumin dialysis on the amino acid profile have been reported in patients with acute and acute-on-chronic liver failure." (PMID 19175915, 2009). "Studies were included if they were randomized controlled trials (RCTs) or clinical trials evaluating the role of human albumin infusion in patients with decompensated cirrhosis, acute-on-chronic liver failure (ACLF), refractory ascites, or hepatorenal syndrome type 1 (HRS-1)." (PMID 41140983, 2025). "A variety of factors contribute to this finding, including differences in HRS-AKI diagnostic criteria that delayed the timing of terlipressin administration, the presence of acute-on-chronic liver failure (ACLF) with associated multiorgan dysfunction, and cumulative albumin dosage." (PMID 38285703, 2024).